FAM90A22 (family with sequence similarity 90 member A22)
Synonyms: FAM90A22P
Tractability: No criterion of Open Targets' tractability assessment is met for any kind of drug.
Gene: Protein-coding gene on chromosome 8 (7,571,995 to 7,575,006, reverse strand). Ensembl gene ENSG00000285687.
Subcellular location (Human Protein Atlas): Nucleoplasm; Nucleoli
Homologues: Orthologues: mouse Fam90a1b (28% identical), mouse Fam90a1a (27% identical), rat Fam90a1l1 (26% identical). Paralogues in human: FAM90A24 (98% identical), FAM90A23 (98% identical), FAM90A13 (97% identical), FAM90A15 (97% identical), FAM90A14 (97% identical), FAM90A12 (97% identical), FAM90A16 (97% identical), FAM90A17 (97% identical), FAM90A5 (97% identical), FAM90A9 (97% identical), FAM90A8 (96% identical), FAM90A10 (96% identical), and 9 more.